RELN (reelin)
Diseases named in the same sentence as RELN in open-access papers (continued):
Sharing a sentence is not in itself a finding about the gene and the disease.
liver fibrosis (6 papers, 2021 to 2025). "As only some HSCs express mGFP and HSCs are the main cause of liver fibrosis, we want to know the difference between Desmin+ HSCs and mGFP+ HSCs (Reelin‐expressing HSCs and their progeny) in fibrotic livers." (PMID 37246473, 2023). "Reelin as a serine protease is associated with liver fibrosis." (PMID 37246473, 2023). "Furthermore, a separate study suggests that Reelin expression in the liver is positively associated with the stage of liver fibrosis." (PMID 37246473, 2023). "While this study administered a low dose of reelin to upregulate reelin signaling and ameliorate behavior associated with chronic stress, significant increases in reelin expression can be a risk factor for the development of certain cancers and hepatic fibrosis." (PMID 37550058, 2023). "This indicates that Reelin is involved in the occurrence of liver fibrosis and is expected to be included into the diagnosis and monitoring of liver fibrosis." (PMID 40625923, 2025). "Although Reelin is primarily known for its role in brain, accumulating evidence indicates its involvement in liver fibrosis." (PMID 37246473, 2023). "Reelin was increased in the synovial fluid of rheumatoid arthritis patients and the serum of HCV liver fibrosis patients, and 180 kDa reelin was increased in the plasma of liver cirrhosis patients." (PMID 38137152, 2023). "Taking into account that reelin activates human progenitor cells upon liver injury and the number of hepatic stellate cells increase as liver fibrosis progressed, reelin could serve as a potential candidate in liver pathology." (PMID 34639052, 2021). "Additionally, RELN impacts the immune system, liver fibrosis, and cancers." (PMID 40171042, 2025).
melanoma (6 papers, 2011 to 2022). A malignant, usually aggressive tumor composed of atypical, neoplastic melanocytes. "Melanoma patients with RELN mutations exhibited a favorable ICI survival benefit when compared with wild-type patients (HR: 0.66, 95% CI: 0.51–0.87, p = 0.003)." (PMID 36497098, 2022). "Significant ICI survival benefits were observed in melanoma patients who harbored RELN mutations (median survival time: 34.9 vs. 24.4 months, Log-rank test p < 0.001)." (PMID 36497098, 2022). "In melanoma, genomic mutational analysis showed that patients with RELN mutations had a markedly higher TMB than RELN wild-type patients (Wilcoxon rank-sum test, p < 0.001)." (PMID 36497098, 2022). "Results showed that pro-inflammatory immunocytes (e.g., CD8 T cells and T follicular helper cells) were significantly enriched in RELN-mutated melanoma patients (Wilcoxon rank-sum test, both p < 0.05)." (PMID 36497098, 2022). "In this study, the RELN mutation association with ICI treatment efficacy in melanoma and non-small cell lung cancer (NSCLC) was elucidated." (PMID 36497098, 2022). "GSEA results indicated that immunogenicity-related signaling pathways of interferon γ/α response and allograft rejection were observed in RELN-mutated melanoma patients (all FDR < 0.001)." (PMID 36497098, 2022). "We observed that the higher infiltration abundance of CD8 T cells and the lower abundance of immune-suppressive M2 macrophages were enriched in melanoma patients with RELN mutations." (PMID 36497098, 2022). "To explore whether RELN mutations play a role in other therapeutic types, we acquired mutational profiles and clinical features data of melanoma and NSCLC samples from the TCGA." (PMID 36497098, 2022). "We performed multivariable Cox regression models in melanoma and NSCLC cohorts with multiple confounding factors, including RELN and FAT1 mutations, taken into account." (PMID 36497098, 2022). "The CIBERSORT algorithm was used to evaluate distinct immunocyte infiltration levels between RELN subgroups in melanoma." (PMID 36497098, 2022). "In our analysis, RELN mutations were found to be connected with the preferable ICI therapy outcome and response in both melanoma and NSCLC patients, which suggests the immunotherapeutic significance of RELN mutations in clinical practice." (PMID 36497098, 2022). "In this work, we uncovered that RELN mutations were predictive of a better ICI treatment outcome and response in melanoma and NSCLC." (PMID 36497098, 2022). "In one of our studies carried out in malignant melanoma (grade Clark IV invasive tumors), reelin was inconstantly expressed and unequally located within the tumoral mass." (PMID 28255385, 2017). "In this study, RELN mutations were identified to connect with a better immune microenvironment and an improved ICI efficacy in melanoma and NSCLC, which provides a potential biomarker for immunological feature evaluation and immunotherapeutic outcome prediction at the molecular level." (PMID 36497098, 2022). "By performing survival analysis based on gene pair mutation, we observed that the mutation of nine gene pairs, such as “SERPINB3|RELN”, “KAT6B|RELN”, and “SERPINB3|PEG3”, were significantly correlated with patient survival in all four independent melanoma datasets (log-rank test p-value < 0.05)." (PMID 36139377, 2022). "We observed that both mutations exhibited preferable ICI treatment prognoses in melanoma and NSCLC patients after mutually adjusting (all HR < 1, all p < 0.05), which suggests that RELN and FAT1 mutations are two independent biomarkers for predicting ICI response." (PMID 36497098, 2022). "Melanoma cells were surface stained for TSPAN8, RELN and FXYD5 or intracellularly stained for renalase, CAPG, BCL11A and ID3." (PMID 21081927, 2011).
otosclerosis (6 papers, 2013 to 2023). Formation of spongy bone in the labyrinth capsule which can progress toward the stapes (stapedial fixation) or anteriorly toward the cochlea leading to conductive, sensorineural, or mixed hearing loss. "A genome-wide association study (GWAS) including a total of 1149 otosclerosis patients identified several intronic variants within the gene encoding Reelin (RELN) that were associated with otosclerosis in European populations." (PMID 36653343, 2023). "Allele and Genotype frequencies distribution of RELN gene polymorphisms in non-syndromic otosclerosis cases and controls." (PMID 35658052, 2022). "RELN was first associated with otosclerosis after performing a pooled GWAS and replicated in several studies." (PMID 36498562, 2022). "The replication of RELN association studies in otosclerosis, the recent GWAS and again in this current study, proves the role of the gene in the disease." (PMID 36498562, 2022). "Subsequent replication of this genetic association between RELN and otosclerosis has been inconsistent." (PMID 29728750, 2018). "Although expressed in the inner ear, the molecular mechanism by which Reelin affects otosclerosis susceptibility is unknown." (PMID 36653343, 2023). "The most recent GWAS was performed as a meta-analysis from three different biobanks: FinnGen, EstBB and UKBB, resulting in the identification of 18 loci associated with otosclerosis, including genes that were previously associated with otosclerosis, e.g., RELN, TGFβ1 and MEPE." (PMID 36498562, 2022). "However, a significant association (p = 0.0057) was detected between one RELN SNP (rs39399) and otosclerosis in familial patients." (PMID 29728750, 2018). "Our findings strengthen the association of TGFB1 (rs1800472) with otosclerosis and support a relationship between RELN and familial otosclerosis only, which may explain previous variable replications." (PMID 29728750, 2018). "Immunofluorescence study has also revealed that reelin immunoreactivity in the stapes of patients with otosclerosis was significantly lower than that of controls." (PMID 35658052, 2022). "Here, we genotyped eight previously associated variants in the following six candidate genes: RELN, BMP2, FGF2, COL1A1, TGFB1, and PPP2R5B in a large UK case–control otosclerosis cohort (n = 748)." (PMID 29728750, 2018). "Considering that the reelin signalling pathway is active in adult otosclerosis and inferior colliculi impairments, it could affect transport through GJ in inner-ear embryogenesis as well." (PMID 35327391, 2022). "Accumulating evidences from the studies suggests that signalling by reelin might be playing an important role in the pathogenies of otosclerosis." (PMID 35658052, 2022). "It is known that yotari mice have disturbances in layer 5 of the inferior colliculi cortex, which is a hearing pathway, and that reelin is involved in cases of adult otosclerosis due to the coordinative role of reelin in the early embryonic stages of development." (PMID 35327391, 2022). "It has been reported that COL1A1, BMP2, BMP4, TGFB1, and RELN genes may also contribute to the development of otosclerosis." (PMID 23864959, 2013).
prostate carcinoma (6 papers, 2011 to 2025). A carcinoma that arises from epithelial cells of the prostate gland. "Additionally, miR-381 facilitates autophagy and apoptosis by suppressing the RELN-mediated PI3K/Akt pathway in prostate cancer cells." (PMID 34753384, 2021). "Thus, epithelial prostate cancer cells show a massive expression of reelin." (PMID 28255385, 2017). "RELN and ALDH1A1 are expressed in prostate cancer, ENG, SI, FCGBP and PTPRT are associated with colonic tumors." (PMID 21533145, 2011). "Thus, reelin was increased in prostate carcinoma, but not in benign prostatic hyperplasia." (PMID 28255385, 2017).
colon cancer (5 papers, 2011 to 2023). "Reelin expression during colon cancer progression appears to be, at least “in part”, regulated by the DNMT-1-mediated methylation of its promotor region." (PMID 36290310, 2022). "The aim of the current study was to elucidate the role of reelin in colon cancer initiation and progression." (PMID 36290310, 2022). "We also attempted to unravel the mechanism that regulates reelin expression during colon cancer progression, as well as the signaling molecules activated by reelin." (PMID 36290310, 2022). "The aim of the current study was to elucidate the role of the protein reelin in colon cancer initiation and progression using mouse models and human samples that extend from colitis or precancerous lesions to colon cancer." (PMID 36290310, 2022). "In this study, we evaluated reelin expression during the transition from either colitis or precancerous lesions to colon cancer and tried to elucidate reelin regulation under these transition processes." (PMID 36290310, 2022). "In conclusion, reelin mRNA abundance depends on the severity of the colon pathology, and its upregulation in response to initial injuries might prevent the beginning of colon cancer, whereas reelin repression favors it." (PMID 36290310, 2022). "The results might contribute to understanding the mechanisms involved in colon cancer, and suggest that reelin may be a biomarker of colon pathology progression." (PMID 36290310, 2022). "This is the first report showing that reelin mRNA abundance depends on the severity of the colon pathology, suggesting that reelin upregulation in response to initial injuries might prevent the beginning of colon cancer, whereas reelin repression favors it." (PMID 36290310, 2022). "Our data rule out such a role during colon cancer progression: ApoER2 mRNA abundance in polyps is similar to that of colitis-associated adenocarcinomas, even though their reelin expression changes in opposite directions." (PMID 36290310, 2022). "Our finding might offer additional evidence of the mechanism of epigenetic regulation of RELN in colon cancer." (PMID 32321427, 2020). "Thus, reelin and DNMT-1 mRNA levels change in opposite directions throughout colon cancer progression in both humans and mice, and the shift in the expression of both genes occurs at the same stage." (PMID 36290310, 2022).
glioma (5 papers, 2021 to 2024). A benign or malignant brain and spinal cord tumor that arises from glial cells (astrocytes, oligodendrocytes, ependymal cells). "Furthermore, more research is required to determine whether mutations in RELN are related to the occurrence and progression of gliomas." (PMID 40217319, 2024). "This case also raised the possibility that RELN mutations and gliomas may be connected." (PMID 40217319, 2024). "Following the analysis of differentially expressed circRNAs in GEO dabase (GSE109569), circ_0081769 (circRELN, derived from reelin (RELN) mRNA) with decreased expression in glioma tissues attracted our attention." (PMID 34479497, 2021). "As a result, we concluded that a mutation in RELN, rather than only the glioma, was the cause of the proband's mother's seizures." (PMID 40217319, 2024). "It suggests that more research and confirmation are needed to determine whether RELN is also connected to the occurrence and progression of gliomas." (PMID 40217319, 2024). "RELN regulated the migration of glioma cells, and activation of the RELN-related pathway could suppress the proliferation of GBM cells." (PMID 34631528, 2021). "Additionally, there are few clinical studies regarding the connection between RELN and glioma." (PMID 40217319, 2024).
Huntington disease (5 papers, 2017 to 2025). Huntington disease (HD) is a rare neurodegenerative disorder of the central nervous system characterized by unwanted choreatic movements, behavioral and psychiatric disturbances and dementia. "RELN expression and function are crucial in degenerative CNS diseases such as AD, PD, and Huntington’s disease." (PMID 40171042, 2025). "The abstinence effects were observed for Huntington’s Disease Signaling and Reelin Signaling in Neurons pathways." (PMID 32647308, 2020). "Interestingly, CCL5 treatment also enhanced neuron development-related signaling, such as CNTF, VEGF, Huntington’s disease, and Reelin." (PMID 39285280, 2024).
lung carcinoma (5 papers, 2016 to 2021). "Of course, consistency across different platforms would be desired of any useful biomarker and so this observation is worrisome if RELN indeed is associated with lung cancer survival." (PMID 30517129, 2018).
Angelman syndrome (4 papers, 2016 to 2020). A neurogenetic disorder characterized by severe intellectual deficit and distinct facial dysmorphic features. "Furthermore, recent evidence has shown that intraventricular reelin infusions facilitate hippocampal-dependent cognition in a mouse model of Angelman syndrome." (PMID 26941609, 2016). "This group further showed that RELN administration ameliorated both the synaptic plasticity and the cognitive behavioral deficits in a mouse model of Angelman syndrome, which is characterized by mental retardation, absence of speech, seizures, and motor dysfunction." (PMID 32082176, 2020).
autosomal dominant lateral temporal lobe epilepsy (4 papers, 2019 to 2025). "Moreover, heterozygous RELN variants account for 17.5% of familial cases of autosomal dominant lateral temporal lobe epilepsy (ADLTE) with relatively low penetrance." (PMID 38980724, 2024).
colorectal cancer (4 papers, 2019 to 2025). A primary or metastatic malignant neoplasm that affects the colon or rectum.
lissencephaly 2 (4 papers, 2013 to 2025). "The reelin protein plays critical roles in neuronal migration and layer formation and has been associated with the human LIS forms LIS2 and Norman-Roberts syndrome." (PMID 24260534, 2013).
medulloblastoma (4 papers, 2007 to 2023). A malignant, invasive embryonal neoplasm arising from the cerebellum. "Reelin has recently been implicated in promoting metastasis in medulloblastoma, a rare pediatric tumor of the cerebellum, that metastasizes almost exclusively to the spine or intracranial leptomeninges." (PMID 37728789, 2023). "We also observed activation of the Reelin pathway, another hallmark of granule neuron development in the cerebellum, in all medulloblastoma molecular subgroups, except for WNT tumors." (PMID 25412507, 2014). "Patched, implicated in the carcinogenesis of medulloblastoma, reelin, expressed in normal retinal development and in response to tissue injury, were also found to be upregulated in RB in our microarray analysis." (PMID 17615543, 2007). "Group 4 medulloblastoma expressed late granule neuron markers and reelin pathway members most highly, which are normally expressed in granule cell precursors during cerebellar development and into post-natal stages." (PMID 25412507, 2014). "We noted that several reelin pathway members are significantly over-expressed in SHH, Group 3 and Group 4 medulloblastoma, but are not expressed in the WNT subgroup." (PMID 25412507, 2014).
neuronal migration disorders (4 papers, 2010 to 2024). "We identified inherited and de novo RELN missense variants in heterozygous patients with neuronal migration disorders (NMDs) as diverse as pachygyria and polymicrogyria." (PMID 38980724, 2024). "We conclude that the pig might serve as an alternative animal model to study Reelin functions and that manipulation of the pig Reelin could allow the establishment of an animal model for human neuronal migration disorders." (PMID 20550682, 2010).